SEMA3E (semaphorin 3E)
Diseases named in the same sentence as SEMA3E in open-access papers (continued):
Sharing a sentence is not in itself a finding about the gene and the disease.
pancreatic cancer (3 papers, 2016 to 2022). "In this study, we showed that Sema3E is overexpressed in human pancreatic cancer, and that high Sema3E levels are associated with tumor progression and poor survival." (PMID 27911862, 2016). "By analyzing Sema3E expression in three separate sources of patient samples, we found that Sema3E was overexpressed in pancreatic cancer, and that patient samples expressing high levels of Sema3E were associated with poor survival." (PMID 27911862, 2016). "In addition, our study reveals the associated high Sema3E levels with worse survival in pancreatic cancer." (PMID 27911862, 2016). "In addition, we found that Sema3E, despite being described and characterized as a secreted protein, was expressed in the nucleus of pancreatic cancer cells and that a high N/C ratio of Sema3E expression was associated with poorly-differentiated tumors, aggressive cancer, and a lower survival rate." (PMID 27911862, 2016). "Results reveal an undiscovered role of SEMA3E in promoting pancreatic cancer pathogenesis, suggesting that SEMA3E as a suitable prognostic marker and therapeutic target for pancreatic cancer." (PMID 35057823, 2022). "Among the top 40 significantly up-regulated genes after fisetin treatment of both hepatic and pancreatic cancer cell lines is Axon guidance protein Semaphorin 3E (SEMA3E)." (PMID 28052097, 2017). "In this study, we found that Sema3E was significantly overexpressed in human pancreatic cancer, and high levels of the protein correlated with worse survival." (PMID 27911862, 2016). "Overexpression of wildtype Sema3E in human pancreatic cancer cell lines enhanced cell growth and migration in cell culture conditions, while knockout of Sema3E reduced cell proliferation and migration." (PMID 27911862, 2016). "Sema3E has been reported to be involved in several different cancers in the past few years, but our study is the first to report the functions of Sema3E in pancreatic cancer." (PMID 27911862, 2016). "Overexpression of Sema3E in pancreatic cancer cells promoted cell proliferation and migration in vitro, and increased tumor incidence and growth in vivo." (PMID 27911862, 2016). "To assess the clinical significance of Sema3E in pancreatic cancer, we sought to determine Sema3E expression in samples obtained from different sources." (PMID 27911862, 2016). "In conclusion, we have shown that Sema3E is overexpressed in human pancreatic cancer samples, and that high levels of Sema3E expression is associated with poor survival." (PMID 27911862, 2016). "By profiling Sema3E in pancreatic cancer, we show the importance and significance of Sema3E in the pathogenesis of pancreatic cancer, and highlight its potential roles as a prognostic marker as well as a therapeutic target." (PMID 27911862, 2016). "Altogether, these data indicate that Sema3E may play an adverse role in the progression of human pancreatic cancer." (PMID 27911862, 2016). "Our observations of Sema3E overexpression in pancreatic cancer are similar to these reports." (PMID 27911862, 2016). "Our findings point towards the potential use of Sema3E as a prognostic marker for predicting pancreatic cancer survival, as well as the potential targeting of Sema3E or its signaling pathways as a novel treatment for pancreatic cancer." (PMID 27911862, 2016). "To determine the effects of Sema3E on the functions of pancreatic cancer cells, we generated stable Sema3E-overexpressing and corresponding vector control cell lines via transduction of MiaPaCa-2 and Panc-48 cells with a lentiviral vector coding for Sema3E cDNA (-S3E) or vector control (-VCtrl)." (PMID 27911862, 2016). "Collectively, these results reveal an undiscovered role of Sema3E in promoting pancreatic cancer pathogenesis, suggesting that Sema3E may be a suitable prognostic marker and therapeutic target for pancreatic cancer." (PMID 27911862, 2016).
pancreatic cancer (continued). "Sema3E expression levels were determined to be higher in tumors vs. normal controls in both sources of patient samples, indicating that Sema3E may be involved in pancreatic cancer pathogenesis." (PMID 27911862, 2016).
anosmia (2 papers, 2021 to 2022). An inability to perceive odors. "SEMA3E mutations were also reported alongside CHD7 mutations in two brothers with KS phenotype instead (i.e., hypogonadism and anosmia)." (PMID 33869187, 2021).
Anxiety (2 papers, 2011 to 2022). Intense feelings of nervousness, tension, or panic often arise in response to interpersonal stresses. "As a consequence, adult Sema3e-null mice displayed several behavioral problems, including decreased anxiety and memory impairment, which are consistent with the patient phenotype." (PMID 35628442, 2022). "Mice mutant for the Sema3E gene also demonstrate reduced anxiety in the elevated plus maze, which may be attributable to a defect in the fornix of these animals, suggesting a similar possible explanation in Sema6A mutants." (PMID 22132072, 2011).
autoimmune disease (2 papers, 2021 to 2022). A disorder resulting from loss of function or tissue destruction of an organ or multiple organs, arising from humoral or cellular immune responses of the individual to their own tissue constituents. "Among them, semaphorin 3A is important in downregulating autoimmune diseases, semaphorin 3E as a critical factor for protective immunity against intracellular chlamydia muridarum infection, and semaphorin 4C in protecting against allergic inflammation." (PMID 35734166, 2022). "We have provided mechanistic evidence that CCR7 expression is kinetically upregulated in the absence of Sema3E suggestive of a novel target to modulate unwanted DC migration, e.g. in allergic or autoimmune diseases." (PMID 34185781, 2021).
developmental delay (2 papers, 2022 to 2023). "The ADI-R Nonverbal Communication Total was associated with a noteworthy locus—intronic regions of SEMA3E— at chromosome 7q21.11 for which structural variations such as microdeletions have been reported in ASD as well as other disorders implicating developmental delays." (PMID 36153334, 2022). "An eight-year-old girl presenting with developmental delay, vomiting, and abnormal behaviour whose examination showed hypoglycaemia, high serum lactate (5.04 mmol/L), bilateral basal ganglia involvement, and a de novo variant c.760G > C (p.E254Q) of SEMA3E gene was identified." (PMID 36918699, 2023).
fibrosis (2 papers, 2017 to 2025). the formation of excess fibrous connective tissue in an organ or tissue in a reparative or reactive process. "To determine whether Sema3E plays a role in the development of airway remodeling, we first evaluated peribronchial fibrosis, characterized by deposition of collagen, in either HDM- or saline-exposed Sema3e−/− versus WT mice." (PMID 29228740, 2017). "Notably, Sema3E predominantly appeared as P61‐Sema3E in the plasma and lung tissues of IPF patients, as well as in lung homogenates from fibrosis‐induced mice." (PMID 40112179, 2025).
hypogonadotropic hypogonadism (2 papers, 2019 to 2020). Abnormal ovarian or testicular function due to insufficient hormonal stimulation from the hypothalamic-pituitary axis. "In addition, SEMA3A and SEMA3E (Semaphorin 3E), are also reported to be associated with hypogonadotropic hypogonadism." (PMID 32390946, 2020).
Infertility (2 papers, 2022 to 2025). "The findings pinpoint Sema3E‐Plexin‐D1 pathway as a potential therapeutic target for fertility and infertility management." (PMID 40391781, 2025).
lung fibrosis (2 papers, 2017 to 2025). "Based on our observation that P61‐Sema3E predominates in the lung tissue from both IPF patients and BLM‐induced lung fibrosis mice, we aimed to elucidate which Sema3E form is the main pro‐fibrotic active form of Sema3E underlying IPF." (PMID 40112179, 2025). "Previous in vitro studies have shown that Sema3E knockdown suppresses fibroblast activation, proliferation, and migration, while in vivo knockdown of Sema3E in whole lung tissue using AAV9‐shSema3E significantly alleviates lung fibrosis." (PMID 40112179, 2025). "Although Sema3E exhibits diverse pathophysiological functions in various diseases, our study provides direct experimental evidence implicating Sema3E in the pathogenesis of pulmonary fibrosis." (PMID 40112179, 2025). "Collectively, these findings underscore the relevance of Sema3E in fibrogenesis and strengthen its candidacy as a biomarker for pulmonary fibrosis." (PMID 40112179, 2025). "However, it's important to note that while our study implicates Sema3E in the pathogenesis of pulmonary fibrosis, previous studies have reported contrasting findings in lung studies of Sema3E." (PMID 40112179, 2025). "These collective findings strongly indicate that the Sema3E‐PlexinD1 signaling axis plays a crucial role in regulating fibroblast activation, migration, and proliferation, thereby implicating its potential involvement in the pathogenesis of pulmonary fibrosis." (PMID 40112179, 2025). "The anti-fibrotic effect of Sema3E could be investigated in models of idiopathic pulmonary fibrosis in which interstitial fibrosis and collagen deposition causes lung damage and respiratory failure." (PMID 29228740, 2017). "In vivo, both whole‐lung Sema3E knockdown and fibroblast‐specific Sema3E knockout confer protection against BLM‐induced lung fibrosis." (PMID 40112179, 2025). "To elucidate the role of Sema3E in fibroblast differentiation, we used TGF‐β1 stimulation of fibroblasts to induce fibroblast differentiation and employed siRNA targeting Sema3E to investigate its impact on lung fibrosis." (PMID 40112179, 2025). "Taken together, our findings indicate that the absence of Sema3E confers protection against BLM‐induced lung fibrosis in mice, highlighting the potential therapeutic significance of targeting Sema3E in the treatment of pulmonary fibrosis." (PMID 40112179, 2025). "The precise molecular mechanisms by which Sema3E influences pulmonary fibrosis have not yet been elucidated." (PMID 40112179, 2025). "Continuing our investigation into the comprehensive role of Sema3E in BLM‐induced pulmonary fibrosis, we sought to determine whether suppression of Sema3E could mitigate pulmonary fibrosis in mice." (PMID 40112179, 2025).
metastatic cancer (2 papers, 2016 to 2025). A carcinoma which has spread from the original site of growth to another anatomic site. "Furin-like pro-protein convertases, commonly found in advanced invasive and metastatic cancers, regulate SEMA3E." (PMID 40103807, 2025).
metastatic melanoma (2 papers, 2011 to 2021). A melanoma that has spread from its primary site to another anatomic site. "In addition, overexpression of Sema3E in a xenograft model of metastatic melanoma was reported by Casazza group to increase, rather than to inhibit, the metastatic spread as reported by Roodink group." (PMID 33858502, 2021).
peripheral vascular disease (2 papers, 2015 to 2022). Any disorder affecting blood flow through the veins or arteries outside of the heart. "Based on this scientific background, the objective of the present research work was to measure in parallel circulating levels of sNRP1, Sema3E, and Slit2 by enzyme-linked immunosorbent assay (ELISA) in a larger case series of SSc patients, focusing on the peripheral vascular disease features." (PMID 35888144, 2022). "However, further follow-up studies will be necessary to ascertain whether circulating Sema3E could be a useful marker to monitor the evolution of SSc-related peripheral vascular disease." (PMID 26292963, 2015).
systemic sclerosis (2 papers, 2015 to 2025). A chronic disorder, possibly autoimmune, marked by excessive production of collagen which results in hardening and thickening of body tissues. "Our study demonstrated elevated expression of both Sema3E in lung tissue and plasma samples from IPF patients, studies in systemic sclerosis have similarly shown increased Sema3E expression in the serum of patients with systemic sclerosis patients, corroborating our findings." (PMID 40112179, 2025). "The aim of the present study was to investigate whether in systemic sclerosis (SSc) Plexin-D1/Sema3E axis could be involved in the dysregulation of vascular tone control and angiogenesis." (PMID 26292963, 2015).
brain infarction (1 paper, 2022). Tissue necrosis in any area of the brain, including the cerebral hemispheres, the cerebellum, and the brain stem. "In this study, using a mouse model of transient brain infarction, we aimed to investigate whether Sema3E-Plexin-D1 signaling was involved in cerebrovascular remodeling after ischemic injury." (PMID 33978913, 2022).
brain tumors (1 paper, 2012). "Of the 14 mice that were inoculated with either sema3E or sema3D expressing cells only one from each group developed a brain tumor while all the mice that received control cells had tumors." (PMID 22936999, 2012). "Indeed, expression of recombinant sema3D and sema3E in U373MG cells also inhibited very strongly the development of tumors from these cells following their implantation in the brain cortex, suggesting that the effects of the semaphorins on the development of brain tumors may be general." (PMID 22936999, 2012).
Cerebral ischemia (1 paper, 2024). Restriction of arterial blood supply to the brain associated with insufficient oxygenation to support the metabolic requirements of the tissue. "Semaphorin 3A, a gene in the same family and located in the same chromosome of Semaphorin 3E, was nominally associated (second top hit) with HT in the original GWAS, and it has been related to vascular permeability of the blood-brain barrier and brain damage after cerebral ischemia in murine models." (PMID 38103737, 2024).
cerebral tumor (1 paper, 2012). "As a result of the combined subcutaneous and intra-cerebral tumor experiments we concluded that sema3E and sema3D may represent the most potent inhibitors, so we used only these two semaphorins in subsequent experiments." (PMID 22936999, 2012).
cervical cancer (1 paper, 2022). A primary or metastatic malignant neoplasm involving the cervix. "Indeed, if circulating sNRP1 has already been proposed as a possible diagnostic biomarker for different diseases such as cervical cancer, cervical intraepithelial neoplasia, and hepatocellular carcinoma, to our knowledge here we explored for the first time the diagnostic power of circulating Sema3E." (PMID 35888144, 2022).
chlamydial infection (1 paper, 2022). "We found that exogenous Sema3E treatment can significantly improve the condition of mice with intact or deficient Sema3E following chlamydial infection in the lung." (PMID 35983029, 2022). "Our data showed that exogenous Sema3E treatment protects mice from chlamydial infection with lower bacterial burden, reduced body weight loss, and pathological lung changes." (PMID 35983029, 2022). "Cellular analysis showed that Sema3E treatment leads to enhanced Th1/Th17 response but reduced Treg response in lungs following chlamydial infection." (PMID 35983029, 2022). "The present study suggests that higher levels of Sema3E would further enhance immunity to chlamydial infection in vivo." (PMID 35983029, 2022). "This study found that treatment of WT and Sema3E KO mice with recombinant Sema3E-Fc protected the mice from chlamydial infection with lower bacterial burden and inflammation in the lung." (PMID 35983029, 2022). "Another interesting finding in the present study is the inhibitory effect of Sema3E treatment on Treg responses in chlamydial infection." (PMID 35983029, 2022). "The results suggest that Sema3E can modulate cytokine responses differently by preferentially promoting Th1/Th17 while reducing IL-4/IL-10 responses after chlamydial infection." (PMID 35983029, 2022). "We next evaluated whether the exogenous Sema3E treatment of WT and Sema3E KO mice affects the surface expression of co-stimulatory and inhibitory molecules on dendritic cells after chlamydial infection." (PMID 35983029, 2022). "Our studies showed that exogenous Sema3E treatment could be considered a novel therapeutic approach to treat chlamydial infections or be used as a supplement to mitigate the side effect of antibiotics." (PMID 35983029, 2022). "To evaluate the potential of exogenous Sema3E to enhance the capability to fight against chlamydial infection, we treated WT mice and Sema3E KO mice intranasally with either recombinant Sema3E-Fc or control saline-Fc, two hours before Cm infection and day 1 to day 6 consecutively after infection." (PMID 35983029, 2022). "The results suggest that Sema3E plays a critical role in the recruitment and development of Th1/Th17 promoting DCs, including the CD103+ DC subset following chlamydial infection." (PMID 35983029, 2022). "Specifically, we have observed that Sema3E treatment enhances IFN-γ and IL-17 production but reduces IL-10 and IL-4 cytokine response in the lungs and spleen after chlamydial infection." (PMID 35983029, 2022).
Cm (1 paper, 2022). "Together, these data confirm that Sema3E can promote Th1/Tc1 and Th17 cell responses in the local tissues (lung) after Cm infection in vivo." (PMID 35983029, 2022).
cognitive decline (1 paper, 2025). "Both the IVs were strongly associated with SEMA3E protein levels in plasma (P<2x10−15), but only nominally associated with cognitive decline (P<0.02)." (PMID 39787209, 2025). "The strongest nominal MR result suggests that plasma Semaphorin 3E (SEMA3E) levels, as predicted by genotype, may be associated with AD progression (P = 6.5x10−4) and indicates that an increase in plasma SEMA3E levels associates with increased cognitive decline or more rapid AD progression." (PMID 39787209, 2025). "This analysis identified a relationship between a signalling molecule involved in neuronal development—SEMA3E—and cognitive decline." (PMID 39787209, 2025).
deafness (1 paper, 2020). An inherited or acquired condition characterized by the complete loss of the ability to hear from one or both ears. "Of the genes misregulated in Mir183/96dko homozygotes, five are known deafness genes; Myo3a, Slc26a5 and Tmc1 underlie deafness in mice and humans, while mutations in Sema3e cause deafness in people, and mice lacking Ocm exhibit progressive hearing loss." (PMID 33318051, 2020).
diabetic retinopathy (1 paper, 2022). "In contrast, reduced expression of aqueous Sema3E is observed in patients with diabetic retinopathy when compared with nondiabetic controls." (PMID 33978913, 2022).
disc degeneration (1 paper, 2017). "However, the role of ANGPTL7 and Semaphorin 3E in disc degeneration is currently unknown and requires further investigations." (PMID 28358123, 2017).
hearing loss (1 paper, 2024). "First, we identified mostly reduced expression of genes previously associated with loss of function mutations linked to overt hearing loss, including Gfi1, Otog, Mafb, Sema3e, Smpx and Sptbn4, suggesting hidden and overt hearing loss share similar genetic mechanisms." (PMID 39049179, 2024).
ischemia (1 paper, 2022). A hypoperfusion of the BLOOD through an organ or tissue caused by a PATHOLOGIC CONSTRICTION or obstruction of its BLOOD VESSELS, or an absence of BLOOD CIRCULATION. "Moreover, Sema3E-Plexin-D1 signaling is associated with ischemia-induced angiogenesis in the periphery tissue and retina, but its activity in the central nervous system has not been elucidated." (PMID 33978913, 2022). "We found that after ischemia, neurons in the peri-infarct region upregulate Sema3E, and vessels close to the damaged region subsequently express Plexin-D1." (PMID 33978913, 2022).
lymph node metastasis (1 paper, 2017). "Finally, 12 probes were chosen for the final classification and associated with 14 genes including several lymph node metastasis-related genes, such as HOXD1, NMT1, and SEMA3E." (PMID 28951630, 2017).